ARPC5 (actin related protein 2/3 complex subunit 5)
Diseases named in the same sentence as ARPC5 in open-access papers (continued):
Sharing a sentence is not in itself a finding about the gene and the disease.
glioma (continued). "Our data showed that higher ARPC5 expression was associated with higher TMB and lower immune response score in glioma, which meant that means that targeted inhibition of ARPC5 may become an attractive immunotherapy strategy in the treatment of glioma." (PMID 37789267, 2023). "Moreover, Kaplan-Meier curves, ROC curves, Cox regression analyses, and prognostic nomograms were used to observe the correlation between the ARPC5 expression and the prognosis of glioma patients." (PMID 37789267, 2023). "Moreover, regression analysis showed that ARPC5 expression, PRS type, grade, and age might be independent risk factors for poor prognosis of glioma patients." (PMID 37789267, 2023). "In order to explore the mechanism by which ARPC5 may influence prognosis in patients with glioma, we performed enrichment analysis to conclude the ARPC5-related genes were involved in cancer-related cell signaling pathways, such as immune, cell adhesion, and apoptosis." (PMID 37789267, 2023). "Meanwhile, a high ARPC5 expression could predict a poor prognosis in patients with gliomas." (PMID 37789267, 2023). "However, the prognostic values and biological functions of ARPC5 in gliomas remain unclear." (PMID 37789267, 2023). "The Kaplan-Meier curves revealed that high ARPC5 expression predicts a poor prognosis for patients with grade II and III gliomas, and the same result was obtained for different molecular subtypes, such as gender, age, IDH mutation status, 1p/19q co-deletion status, and MGMT methylated status." (PMID 37789267, 2023).
idiopathic pulmonary fibrosis (1 paper, 2025). Idiopathic pulmonary fibrosis (IPF) is a nonneoplastic pulmonary disease that is characterized by the formation of scar tissue within the lungs in the absence of any known cause. "Using the Idiopathic Pulmonary Fibrosis (IPF) Cell Atlas, we found increased expression of phagocytosis-related genes (FCGR1A, ARPC4, ARPC5) in IPF patients across multiple datasets (available at Rheumatology online)." (PMID 39672802, 2025).
sarcopenia (1 paper, 2022). Progressive decline in muscle mass due to aging which results in decreased functional capacity of muscles. "The eQTL analysis for muscle mass using GTEx datasets showed that RPS10, NUDT3, NCF2, SMG7, and ARPC5 were differentially expressed in the muscle tissue for sarcopenia." (PMID 35241739, 2022).
synovitis (1 paper, 2021). Inflammation of a synovial membrane. "In sum, this study indicated that WB had obvious inhibitory effects on synovitis of CIA rats, and the mechanisms of which may be involved in downregulating the expression levels of several key proteins including MMP3, MMP19, LBP, IRAK4, and ARPC5." (PMID 34708132, 2021).
virus infection (1 paper, 2019). "Silencing of ARPC5, involved in actin polymerization, resulted in a reduction in virus infection." (PMID 31132962, 2019).
Wiskott-Aldrich syndrome (1 paper, 2025). Wiskott-Aldrich syndrome (WAS) is a primary immunodeficiency disease characterized by microthrombocytopenia, eczema, infections and an increased risk for autoimmune manifestations and malignancies. "In our model, the intestinal pathology associated with ARPC5 deficiency in hematopoetic cells was restricted to the small intestine (ileum) but not the large instestine, in contrast to what has been reported in a mouse model of Wiskott-Aldrich Syndrome." (PMID 41231985, 2025).
cancer (18 papers, 2017 to 2025). A tumor composed of atypical neoplastic, often pleomorphic cells that invade other tissues. "Prior research has linked increased ARPC5 expression to enhanced cell migration in cancers, implicating it in immune cell infiltration into tumours." (PMID 39672802, 2025). "In contrast, elevated ArpC5 levels have been linked to cancer progression, as ArpC5 depletion has reduced the motility and invasiveness of carcinoma cells." (PMID 36662867, 2023). "We discovered that the expression of ARPC5 was upregulated in most cancer types and high-expressed ARPC5 was associated with poor survival outcomes and tumor progression in some cancers." (PMID 36148220, 2022). "That indicating ARPC5 expression was closely associated with the mutation type in multiple cancer types." (PMID 36148220, 2022). "We first investigated the expression pattern of ARPC5 in pan-cancer and discussed the associations of ARPC5 expression with pan-cancer prognosis and clinicopathological parameters." (PMID 36148220, 2022). "ARPC5 expression was upregulated in most cancer types and significantly associated with worse prognosis in KIRC, KIRP, LGG, and LIHC." (PMID 36148220, 2022). "First, Gene co-expression and Spearman’s coefficient analyses were conducted to investigate the association between ARPC5 expression and 47 ICIs-related genes in 33 cancer types." (PMID 36148220, 2022). "We found that ARPC5 was evidently positively associated with Immune scores in 22 cancers, and related to Stromal scores in 15 cancer types, suggesting ARPC5 might be a critical driver of immune cells and stromal cells." (PMID 36148220, 2022). "In addition, the expression of ZHX3 was found to be inversely related with the expressions of NMI and ARPC5, which have been associated with proliferation and motility of cancer cells, respectively." (PMID 28152006, 2017). "Therefore, our results provide novel insights into why specifically ArpC5 over ArpC5L is associated with enhanced cell motility and could be linked to increased cancer progression and metastasis." (PMID 36662867, 2023). "It, therefore, can be concluded that ARPC5 may associate with tumorigenesis and cancer progression." (PMID 36148220, 2022). "Thus, to further elucidate the potential impact of ARPC5 on the tumor immunity, we first applied the ESTIMATE algorithm to assess Immune and Stromal scores for 33 cancer types and analyzed the association between ARPC5 expression and Immune/Stromal scores using Spearman’s correlation method." (PMID 36148220, 2022). "ARPC5 expression was positively correlated with the tumor microenvironment scores, immune-infiltrating cells and immune checkpoint–related genes in most cancers." (PMID 37575948, 2023). "ARPC5, a member of the Arp2/3 complex, was reported to influence many critical biological processes in cancer, such as cell migration, invasion, and differentiation." (PMID 37789267, 2023). "Note that ArpC5 expression and Ena/VASP expression are associated with increased metastasis and poorer overall survival in different cancers." (PMID 36662867, 2023). "The public databases, including TCGA, GTEx, and UCEC, were used to analyze ARPC5 expression in pan-cancer." (PMID 36148220, 2022). "ARPC5 expression was generally low in C3 subtype, except for KICH, PCPG, TGCT, and ARPC5 was widely highly expressed in C2 subtype of 11 cancer types except CESC, KICH, LGG, and READ." (PMID 36148220, 2022). "The expression of ARPC5 was significantly associated with CD4+ T cell in 20 cancers, CD8+ T cell in 25 cancers, neutrophil cell in 32 cancers, macrophage cell in 27 cancers, and DC cell in 29 cancer types." (PMID 36148220, 2022). "We had clarified that ARPC5 was significantly differentially expressed among 22 cancer types in above analysis." (PMID 36148220, 2022).
cancer (continued). "The results suggested that the expression of ARPC5 was positively associated with the infiltration level of B cell, CD4+ T cell, CD8+ T cell, neutrophil cell, macrophage cell, and DC cell in most cancer types, especially for KIRC, LGG, PRAD, THCA, and THYM." (PMID 36148220, 2022). "ARPC5 expression was significantly positively related to B cell in 22 cancer types, and negatively related to B cell in ESCA." (PMID 36148220, 2022). "The prognosis value of ARPC5 was analyzed in 22 cancers in which ARPC5 expression varied significantly between cancer and normal tissues." (PMID 36148220, 2022). "Then, the differential expression of ARPC5 between tumor and normal tissues of pan-cancer was assessed using Wilcoxon Rank Sum Test." (PMID 36148220, 2022). "We further explored the relationship between expression of ARPC5 and clinicopathology features in pan-cancer, including the clinical stage, histologic grade, and tumor molecular subtype." (PMID 36148220, 2022). "ARPC5 expression was positively correlated with the tumor microenvironment scores, immune infiltrating cells, immune checkpoint–related genes in most cancers." (PMID 36148220, 2022). "Nevertheless, the expression pattern, prognosis values, and biological roles of ARPC5 in most types of cancer have seldomly been analyzed systematically." (PMID 36148220, 2022). "We found that ARPC5 expression was closely correlated with the expression of methyltransferases in most cancer types, especially in KICH and UVM." (PMID 36148220, 2022). "In summary, comprehensive analyses were conducted in our study to explore the expression patterns and prognostic values of ARPC5 in pan-cancer using multiple databases." (PMID 36148220, 2022). "Wilcoxon Rank Sum Tests or Kruskal–Wallis Rank Sum Test was used to compare the expression levels of ARPC5 in different variation status of each cancer." (PMID 36148220, 2022). "In this study, we found ARPC5 expression was closely correlated with tumor stage, histologic grade, and tumor molecular subtype in pan-cancer analyses." (PMID 36148220, 2022). "The correlation between ARPC5 expression and immune scores and stromal scores of tumor microenvironments in pan-cancer." (PMID 36148220, 2022). "It was reported that the expression of ARPC5 was significantly higher in HNSCC tissues than in non-cancer tissues, and ARPC5 was also significantly increased in invasive cancer cells." (PMID 36148220, 2022). "In this study, we conducted pan-cancer analyses of ARPC5 among 33 human cancer types using the Cancer Genome Atlas (TCGA) datasets, Genotype-Tissue Expression (GTEx) datasets, and some online bioinformatic analysis websites." (PMID 36148220, 2022). "The GSEA results indicated that ACTR3, ARPC2, and ARPC5 are involved in multiple cancer-related pathways that promote the development of HCC." (PMID 34307456, 2021). "ARPC5, as one part of Arp2/3 complex, was identified to contribute to cell migration and invasion in many carcinomas." (PMID 34708132, 2021). "Moreover, ARPC1A, ARPC1B, and ARPC5 demonstrated significant copy number amplification in most cancer types." (PMID 39867911, 2024). "Importantly, ARPC5 can promote LC development through multiple cancer-related pathways and be identified as an independent prognostic biomarker of patient survival." (PMID 36605483, 2023). "Thus, it is essential to explore the roles of ARPC5 in pan-cancer from a novel and comprehensive perspective." (PMID 36148220, 2022). "The results indicated that the expression of ARPC5 was upregulated in most cancer types." (PMID 36148220, 2022). "The average optical density value of ARPC5 immunohistochemical staining in cancer tissues was higher than adjacent normal liver tissues, indicating that the ARPC5 expression was higher in tumor tissues than adjacent normal liver tissues, which cohered with the results of Western blot." (PMID 36148220, 2022).
cancer (continued). "Notably, we perform a series of experiments to identify the differential expression of ARPC5 in HCC tissues and HCC cells and further revealed that ARPC5 had a cancer-promoting effect in HCC cells and enhanced HCC progression for the first time." (PMID 36148220, 2022). "Therefore, it is critical to systematically investigate the role of ARPC5 in different types of cancer." (PMID 36148220, 2022). "Moreover, we further explored the relationship between genomic variation and ARPC5 expression in pan-cancer via integrating CNV and gene expression data." (PMID 36148220, 2022). "In addition, we further probed into the relevance of ARPC5 expression with different immune subtypes of pan-cancer." (PMID 36148220, 2022). "We speculated that ARPC5 might contribute to cancer progression through influencing the genes stability." (PMID 36148220, 2022). "However, little is known about the expression pattern, prognosis value, and biological function of ARPC5 in pan-cancer." (PMID 36148220, 2022). "We also found that the expression of ARPC5 was significantly related to MSI in 12 types of cancer." (PMID 36148220, 2022). "Additionally, aspirin treatment also significantly decreased the expression of genes encoding cytoskeleton including ARPC5, NEXN and LRPPRC, which may be helpful to understand the mechanisms behind aspirin suppressing the metastasis of cancer cells." (PMID 28184026, 2017). "Higher expression of these subunits correlates significantly with poor patient survival and advanced cancer stages, with ACTR3, ARPC2, and ARPC5 showing positive correlations with immune cell infiltration." (PMID 41332982, 2025). "Multiple actin-related proteins including ARPC1B, ARPC5, ACTL6A, and CFL1, which are markers for aggressive cancers, were part of the upregulated network nodes." (PMID 33317623, 2020). "The subnetwork involves an interesting combination of the downregulation of the cancer gene EGFR and the amplification of a group of genes involved in T-cell receptor signaling (PTPRC, CD247, and ARPC5)." (PMID 30978274, 2019). "Moreover, ARPC5 had a correlation with TMB in 12 cancers, MSI in 12 cancers, and neoantigens in five cancers." (PMID 36148220, 2022). "Moreover, TIMER database was used to explore the correlation of ARPC5 expression with infiltration levels of B cell, CD4+ T cell, CD8+ T cell, neutrophil cell, macrophage cell, and DC cell in pan-cancer." (PMID 36148220, 2022). "For example, in the case of the reduced set obtained with machine learning, ARPC5 is a protein whose normal function is involved in EPH-Ephrin signaling and tight junction regulation and they are involved in cancer processes as adhesion, migrations, invasion or growth." (PMID 33649335, 2021). "Furthermore, immunohistochemistry for ARPC5 was conducted in 40 paired HCC samples to verify the results; we found that immunohistochemical staining of ARPC5 was obviously observed in the cytoplasm of HCC cancer tissues, whereas no or weak staining was found in adjacent non-cancerous tissues." (PMID 36148220, 2022).
tumor (12 papers, 2015 to 2025). "We found that ARPC5 was significantly expressed in 22 tumor tissues compared with corresponding normal tissues and the expression levels was associated with tumor prognosis in multiple cancers." (PMID 36148220, 2022). "Several evidence reveals that ARPC5 is associated with tumor progression, metastasis, and prognosis, indicating that ARPC5 may represent a promising biomarker and therapeutic target." (PMID 36148220, 2022). "Then, a series of in vitro and in vivo experiments were performed to test the regulatory effect of the lncRNA_DSCR8/miR-22-3p/ARPC5 axis in LC cell lines (hep3B and Huh7 cells) and nude mice with Hep3B xenografted tumor." (PMID 36605483, 2023). "To further explore the relationship between ARPC5 and immune, we analyzed the effect of ARPC5 expression on tumor microenvironment." (PMID 37789267, 2023). "In order to further analyze the expression of ARPC5 in tumor tissues, we retrieved the TIMER database and observed that ARPC5 was abnormally expressed in 19 tumor types, including in GBM." (PMID 37789267, 2023). "Meanwhile, we also explored the relationship of ARPC5 expression with gene mutation, gene modification, TME, tumor immune infiltration cells, ICIs response, and tumor stemness scores." (PMID 36148220, 2022). "The higher the expression of ARPC5, the more advanced tumor stage for the patients with KIRC and KIRP." (PMID 36148220, 2022). "The results indicated the increased expression of ARPC5 was positively correlated to tumor stage of KIRC (ρ = 0.311, p = 2.46e-13) and KIRP (ρ = 0.206, p = 8.51e-04)." (PMID 36148220, 2022). "The ARPC5 expressed in all normal tissues and cell lines, showing low RNA tissue and cell specificity in human normal tissues, tumor cell lines, and single cell types." (PMID 36148220, 2022). "ARPC5 expression affects the prognosis of multiple tumors and is closely correlated to tumor immune infiltration and immunotherapy." (PMID 36148220, 2022). "Within our collection of tumor samples, the ARPC5 expression recurred in 78% of cases at the high expression level, while it proved to be absent, or at the detection limit, in the normal tissues." (PMID 28686225, 2017). "Besides, CPEB2 silencing also reduced MM tumor growth by decreasing ARPC5 expression." (PMID 37231521, 2023). "Spearman’s correlation analysis was performed to investigate the association between ARPC5 expression and tumor microenvironment scores, immune cell infiltration, immune-related genes, TMB, MSI, RNA modification genes, DNA methyltransferases, and tumor stemness." (PMID 36148220, 2022). "Therefore, we further measured the correlation between ARPC5 expression and tumor neoantigens." (PMID 36148220, 2022). "The similar results were presented in the correlation between ARPC5 expression and histologic grades in KIRC, LGG, LIHC, and USEC, indicating that ARPC5 can promote tumor progression and facilitate tumor malignancy." (PMID 36148220, 2022). "In addition, we found that ARPC5 was closely related to TME, tumor infiltration immune cells, immune subtypes, and biomarkers of ICIs, which might provide a new insight of ARPC5 with tumor immunity and would be favorable for mining novel therapeutic target and predictive biomarker for immunotherapy." (PMID 36148220, 2022). "Furthermore, ARPC5 may function as an oncogene and promote tumor progression in HCC." (PMID 36148220, 2022). "Apart from WDR1, several other oncoproteins and tumour suppressors, such as LDHA, CLIC1, ARPC5, ZYX, RCN1, FHIT and CFTR, were identified in this study." (PMID 32601462, 2020). "In contrast, positive immunostaining for CORO1C, RAD23B, and ARPC5 was observed in 55.7% (535/961), 84.0% (420/500), and 85.8% (429/500) of the CRC tumor tissues, respectively, showing significant upregulation compared with the adjacent noncancerous tissues (all P < 0.0001)." (PMID 35589723, 2022).
tumor (continued). "Currently, there are no relevant studies on the CORO1C, RAD23B, and ARPC5 proteins in CRC, except for our very recent work, which showed that RAD23B was overexpressed in CRC tumor tissues and associated with pathological grade, TNM staging, liver metastasis, and poor overall survival." (PMID 35589723, 2022). "Combined with the findings that the CORO1C, RAD23B, and ARPC5 concentrations in urine show good performance in distinguishing early-stage CRC (stage 0 and stage I) from HCs, these findings strongly suggest alterations in urinary proteins may occur at the tumor initiation stage." (PMID 35589723, 2022).
infection (5 papers, 2016 to 2025). The state of being infected such as from the introduction of a foreign agent such as serum, vaccine, antigenic substance or organism. "Then, we investigated the expression of Arpc4 and Arpc5 during infection with V. splendidus." (PMID 34898657, 2021).
ARPC5 also shares sentences with these, for which no sentence is quoted: non-small cell lung carcinoma (2 papers); pancreatic cancer (2); Salmonella Infections (2); small cell lung carcinoma (2); actinopathy (1); acute myeloid leukemia (1); anemia (1); genetic disorders (1); gingivitis (1); invasive breast carcinoma (1); microcephaly (1); periodontal disease (1); renal cell carcinoma (1); tongue SCC (1); Zinc deficiency (1).